FTO (FTO alpha-ketoglutarate dependent dioxygenase)
Diseases named in the same sentence as FTO in open-access papers (continued):
Sharing a sentence is not in itself a finding about the gene and the disease.
Obesity (continued). "In the Swedish obesity intervention study, the FTO obesity predisposing allele carriers lost 3kg less than common allele homozygotes after obesity surgery, and this association was restricted to those undergoing banding surgery but was not significant in the gastric bypass operated subjects." (PMID 22043165, 2011). "In the present study, we examined single nucleotide polymorphisms (SNPs) in the adiponectin, LEPR, MC4R and FTO genes in association with obesity in a cohort of young South African Asian Indian patients with acute myocardial infarction (AMI), with and without the metabolic syndrome." (PMID 21298202, 2011). "This meta-analysis investigated the associations between five FTO polymorphisms (rs9939609, rs1421085, rs8050136, rs17817449, and rs1121980) and obesity risk in 41,734 cases and 69,837 controls from 59 studies, counting the cases and control subjects from each study only once." (PMID 21651756, 2011). "Recently, several independent large-scale genome-wide association studies (GWAS) reported an association of fat mass and obesity associated (FTO; MIM: 610966) and melanocortin-4 receptor (MC4R; MIM: 155541) gene polymorphisms with obesity and BMI in Caucasian populations." (PMID 21347432, 2011). "Furthermore, in 2007, the FTO (fat mass and obesity associated) gene was found to encode a functional homologue of AlkB, and two more genes, TET1 and TET2, suggested possibility as a similar mechanism." (PMID 21285982, 2011). "Also, mRNA levels of RBL2, that was suggested to mediate the biological consequences of a FTO variant on obesity risk, remained unchanged." (PMID 21687707, 2011). "Finally, we were surprised that the FTO A-allele tended to lower IL-6 levels, since we would have expected obesity to lead to increased IL-6 levels." (PMID 21246032, 2011). "To confirm or refute unambiguously whether PA attenuates the association of FTO with obesity risk, we meta-analyzed data from 45 studies of adults (n = 218,166) and nine studies of children and adolescents (n = 19,268)." (PMID 22069379, 2011). "To determine whether the associations between obesity and prostate cancer are causal, we conducted a genetic association study of the relationship between a single nucleotide polymorphism known to be associated with obesity (FTO rs9939609) and prostate cancer." (PMID 20976066, 2010). "Genetic variation in the FTO gene associates with obesity in Chinese children." (PMID 20858286, 2010). "In 2007, an association of single nucleotide polymorphisms (SNPs) in the fat mass and obesity-associated (FTO) gene region with body mass index (BMI) and risk of obesity was identified in multiple populations, making FTO the first locus unequivocally associated with adiposity." (PMID 20381893, 2010). "Our study only obtained 44% power to detect the association between FTO genotype and obesity." (PMID 20858286, 2010). "The objective of the study was to investigate whether FTO variants are associated with a broad range of obesity related anthropometric traits in an island population." (PMID 20442772, 2010). "We aimed to characterise the possible longitudinal associations of common diabetes-susceptibility variants in the KCNJ11, PPARG, TCF7L2, IGF2BP2, CDKAL1, SLC30A8 and HHEX gene loci, with fasting glucose level; and of an obesity-associated variant in the FTO gene, with body mass index (BMI)." (PMID 20929593, 2010). "Previous genome-wide association studies for type 2 diabetes susceptibility genes have confirmed that a common variant, rs9939609, in the fat mass and obesity associated (FTO) gene region is associated with body mass index (BMI) in European children and adults." (PMID 20598163, 2010). "We demonstrate the ability to replicate in our population the association of FTO variants with obesity, which is the main BMI-associated locus, thus further proving the robustness of the association and the appropriate selection of our samples to study obesity." (PMID 21118518, 2010).
Obesity (continued). "However, it did not draw much attention until very recently when its human homolog FTO was implicated in obesity." (PMID 21103374, 2010). "In addition, variation in GCKR, encoding glucokinase regulatory protein, and FTO, the fat mass and obesity associated gene, were associated with serum triglyceride and BMI respectively." (PMID 20161779, 2010). "Future studies focusing on these phenotypes might help clarify the mechanisms through which common variants of the FTO gene and obesity are related." (PMID 20598163, 2010). "The associations of FTO and obesity-related phenotypes were further replicated in various populations including Caucasians and Asians, but could not be confirmed in an African population." (PMID 20377915, 2010). "Obesity is highly heritable and recent GWASs have identified variants in approximately 15 genes that are associated with body mass index (BMI), among which are FTO, MC4R and CTNNBL1." (PMID 21118518, 2010). "Furthermore, diabetes risk-associated FTO alleles were also strongly associated with increased body mass index (BMI), a measure of obesity, strongly suggesting that the association of FTO GVs with type 2 diabetes risk is secondary to effects on BMI." (PMID 21286314, 2010). "The mechanisms of how FTO variants influence BMI and obesity-related traits are unclear." (PMID 20598163, 2010). "The objective of this study was to replicate the association between FTO SNPs and “body fatness” measures in our sampled population and to examine whether FTO variants affected other obesity related anthropometric measures." (PMID 20442772, 2010). "In analyses using full covariate models, we observed that the T T2D-risk allele at the IGF2BP2 SNP rs4402960 was associated with raised fasting glucose level (p = 0.045), and that the A obesity-risk allele at the FTO SNP rs9939609 was associated with raised BMI (p = 0.003)." (PMID 20929593, 2010). "The studies so far seemed to connect the deficiency of FTO with protection of obesity in mice." (PMID 21103374, 2010). "A recently implicated gene in humans for obesity, FTO, is also part of the PER1 signature." (PMID 19203388, 2009). "Because the obesity-associated SNPs are intronic, it is unclear whether changes in FTO expression or splicing are the cause of obesity or if regulatory elements within intron 1 influence upstream or downstream genes." (PMID 19680540, 2009). "Also, although recent genome wide association studies have identified common genetic variation in the melanocortin 4 receptor (MC4R) and FTO (the fat mass and obesity associated) genes, an association with the dopamine transporter was not reported." (PMID 19183461, 2009). "Children with the FTO (rs9939609) variant that increases the risk of obesity may have a higher susceptibility to the effects of DED because their internal appetite control system is compromised." (PMID 19259258, 2009). "However, other studies in Chinese, Koreans, Malay, Japanese, as well as Canadians of South Asian and Inuit origin, presented support for a role of polymorphisms in the FTO gene and obesity in such populations." (PMID 19265514, 2009). "This study reveals the multi-factorial origin of obesity and indicates that although FTO may put some children at greater risk of obesity, encouraging a low dietary energy density may be an effective strategy to help all children avoid excessive fat gain." (PMID 19259258, 2009). "Although the role of FTO or nearby genes in susceptibility to obesity remains unknown, several recent studies have begun to shed light on its function." (PMID 18218107, 2008). "However, rs9939609 has, amongst other FTO SNPs, also recently convincingly been shown to be associated with adult obesity." (PMID 18799002, 2008). "FTO has upon identification been found to encode a 2-oxoglutarate-dependent nucleic acid demethylase, however, the link between this enzyme and the development of obesity remains to be elucidated." (PMID 18682847, 2008).
Obesity (continued). "One might also consider that the association of the variants in intron one of FTO points to an obesity gene in the vicinity of the associated SNPs." (PMID 18799002, 2008). "The association of FTO SNPs with obesity has been independently confirmed in 8000 individuals." (PMID 19662211, 2007). "However, we have some circumstantial evidence of a functional link as we recently found that a polymorphism in the FTO gene, which is related to obesity, is associated with a decreased insulin effect on cerebrocortical beta activity." (PMID 18030331, 2007). "The FTO risk (A/-) allele associated with this SNP is linked with increased body fat percentage, body mass, BMI, and other lifestyle factors that may perpetuate an individual's risk for obesity." (PMID 42197023, 2026). "Moreover, 21 significant interactions between the risk allele “C” of the FTO rs1421085 and random eating patterns, a tendency toward fat-dense food, irregular sleep, and shift work were observed to increase obesity-related traits such as BMI, WC, HC, WHR, WHtR, and BF%." (PMID 39283705, 2025). "Therefore, it is crucial to consider obesity status when evaluating whether increased ccRCC risk in patients is associated with FTO SNPs." (PMID 40361322, 2025). "This study analyzed only one SNP of the FTO gene, i.e., rs9939609 was the common polymorphism reported for our population in the literature, and so other genetic variants could also be linked to obesity and other metabolic parameters." (PMID 41190148, 2025). "For instance, the identification of FTO or PPARG risk alleles could guide early lifestyle interventions in individuals at high risk for obesity or type 2 diabetes, while variants in COL1A1 or IL6 may allow the identification of increased susceptibility to tendon or ligament injuries." (PMID 41300761, 2025). "Similarly, RNA modifications and RNA-binding proteins—for instance, m6A dynamics mediated by FTO (fat mass and obesity-associated protein)—modulate mRNA stability and translation of adipogenic regulators, thereby shaping lipid metabolism and differentiation outcomes." (PMID 41300824, 2025). "Furthermore, variations in the FTO gene, which are associated with obesity, may exacerbate the pathological process of GDM by affecting adipokine levels." (PMID 41541195, 2025). "Furthermore, integrating genetic markers such as FTO variants with psychological and lifestyle predictors could enhance the precision of future obesity research." (PMID 41156441, 2025). "However, several studies have shown that the association between FTO gene polymorphism and obesity related outcomes may intensify with age." (PMID 40906427, 2025). "However, the precise relationship among PCOS, obesity, and FTO polymorphism remains ambiguous." (PMID 39660878, 2024). "To date, the FTO gene has been proposed as a candidate gene to affect fat oxidation during exercise because of the association of the “at-risk” A allele with different obesity-related factors such as increased body fat, higher appetite and elevated insulin and triglyceride levels." (PMID 39858551, 2024). "The FTO gene polymorphisms may influence the effects of lifestyle interventions on obesity." (PMID 38556726, 2024). "Considering that variants in FTO showed high correlation with body weight and also interact with dopamine signaling in the brain, a clinical trial was designed to develop a genotype-specific and individualized therapy approach for obesity targeting FTO (rs8050136) variant (NCT03525002)." (PMID 38531882, 2024). "Also, the effect of FTO genotype on the risk of obesity in people with different diets may be different from its effect on the effect of weight loss interventions in obese people." (PMID 38556726, 2024). "However, there is controversy surrounding the risk allele of FTO rs17817449 linked to obesity." (PMID 39706986, 2024).
Obesity (continued). "In addition, the FTO obesity‐associated polymorphisms were associated with the expression of the homeobox gene Iroquois class homeobox protein 3 (IRX3), and the hypothalamic expression of IRX3 gene is reported to be associated with body composition and calorie intake." (PMID 38556726, 2024). "In 2007, human genome-wide association studies (GWAS) revealed that single nucleotide polymorphisms (SNPs) in the human FTO gene were associated with increased body mass index (BMI) and obesity, which is where the gene and its product derive their full name now: fat mass and obesity-associated." (PMID 39744011, 2024). "In some populations, the effect of FTO polymorphisms on BMI may also be masked by dietary habits and physical activity, which may modulate the effect of FTO polymorphisms on obesity, due to the fact that increased physical activity reduced the effect of the A allele of rs9939609 on BMI." (PMID 39458556, 2024). "For example, expression regulation of the FTO gene, a classic gene involved in obesity risk, was thoroughly characterized in adipocytes and brain neurons using functional genomics approaches, leading to key conclusions about pleiotropy in the context of obesity." (PMID 39254840, 2024). "The consumption of unhealthy food groups, typically low in dietary fiber, has also been studied in relation to obesity, demonstrating that subjects with a higher number of FTO risk alleles might be more susceptible to obesity when consuming foods like fried foods and sugary beverages." (PMID 38398881, 2024). "Both the FTO variants 30685 (TT vs GG: odds ratio (OR), 2.30; 95% confidence interval (CI), 1.39-3.79) and -23525 (TT vs AA: odds ratio (OR), 2.78; 95% confidence interval (CI), 1.37-5.64) showed substantial risk towards obesity by conferring it 2 times and 3 times, respectively." (PMID 39253342, 2024). "Polymorphisms within the first intron of the FTO gene have been examined across various populations, yielding disparate findings.The present study aimed to determine the impact of two intronic polymorphisms FTO 30685T/G (rs17817449) and -23525T/A (rs9939609) on the risk of obesity in Punjab, India." (PMID 39253342, 2024). "Two fat mass and obesity associated (FTO) gene locus variants were among these SNPs, confirming the findings of previous intervention studies demonstrating that a hypocaloric diet combined with increased protein intake alleviates the influence of FTO variants on obesity." (PMID 38281958, 2024). "Moreover, “rs1799883” SNP of the fatty acid binding protein 2 (FABP2) gene was found to be associated with hypertriglyceridemia, while “rs9939609” SNP of the fat mass and obesity-associated (FTO) gene was correlated with an increased risk of body fat accumulation." (PMID 38474710, 2024). "Similarly, a systematic review and meta-analysis of 23 studies among different ethnicities (Asians, Caucasians, and Amerindians) suggested that the FTO gene variants showed a positive correlation with overweight and obesity in children, adolescents, and adults." (PMID 39257882, 2024). "However, in this study, individuals with the AA genotype exhibited comparable MFO values to those with the TT genotype, which contradicts the typical model of the FTO rs9939609 polymorphism, where AA carriers are generally associated with greater obesity-related factors compared to TT carriers." (PMID 39858551, 2024). "Finally, we examined whether the association between FTO SNVs and cardiometabolic disease is mediated by obesity indicators and whether the mediating effect varies by sex." (PMID 38064210, 2023). "Interestingly, alcohol consumption and AD risk may moderate the effects of FTO obesity-risk SNPs on BMI." (PMID 38389820, 2023).
Obesity (continued). "Because we observed significant effects of FTO rs1421085 SNP on the gene expression pattern of active beige SC adipocytes, we also compared the transcriptomic data of active beige and white or inactive beige adipocytes that carried FTO risk-free or obesity-risk genotypes, respectively." (PMID 37416800, 2023). "We report altered structural connectivity as one mechanism by which FTO variants contribute to increased impulsivity, indicating that FTO variants may exert their effect on obesity-promoting behavioral traits at least partially through neuroplastic alterations in humans." (PMID 37223038, 2023). "Therefore, it seems necessary to compare the results obtained with other potential indicators in the future, like molecular indicators including variants of different risk alleles to determine polygenic or common obesity, including FTO, TNF-α, MC4R, ENPP1 genes, etc.." (PMID 37761477, 2023). "Thus, children with more copies of the FTO rs9939609 risk allele (A) may be at a greater risk for developing obesity due to enhanced reactivity to food cues—potentially leading to increased consumption of energy-dense foods." (PMID 37145386, 2023). "Therefore, it is possible that increased expression of FTO caused by obesity-associated SNPs49,50 may contribute (to some extent) to the increased risk of individuals with overweight and obesity developing various types of disorders of sex development." (PMID 38129517, 2023). "Besides, FTO as an obesity-associated gene, also affects osteogenesis by regulating adipogenesis." (PMID 38020896, 2023). "Hence, FTO polymorphism might - directly and indirectly - affect obesity development via neurodevelopmental pathways." (PMID 37223038, 2023). "Having observed that FTO rs1421085 SNP affected the expression of thermogenic genes, our next aim was to investigate whether the expression of mitochondrial complex subunits and cellular respiration were also suppressed in adipocytes with obesity-risk alleles." (PMID 37416800, 2023). "Additionally, evidence from animal studies also indicates an indirect role of FTO polymorphism in neuronal plasticity promoting obesity by regulating genes or enhancers involved in neurogenesis relevant for body weight homeostasis without affecting FTO expression." (PMID 37223038, 2023). "In addition, some genes such as fat mass and obesity‐associated (FTO) may have a dual effect on nutritional requirements and breast cancer risk." (PMID 36403211, 2022). "Moreover, they showed that siRNA-mediated knockdown of FTO led to the increased levels of m6A in mRNA, while overexpression of FTO resulted in a decreased level of m6A in human cells, suggesting m6A in nuclear RNA as a major physiological substrate of the obesity-associated FTO." (PMID 36076918, 2022). "In addition, other pathways were identified such as DNA damage response, neural crest differentiation, mesoderm commitment, TGF-β signaling, FTO obesity variant mechanism, transcription factor regulation of adipogenesis, estrogen signaling, and BMP signaling and regulation." (PMID 35205324, 2022). "Monogenic disorders related to mutations in the FTO regions have also been identified in humans, and polymorphisms in the noncoding areas of this gene have been linked with obesity and several other diseases, particularly those for which obesity is a risk factor." (PMID 36362270, 2022). "In addition, FTO is not only closely related to obesity and tumors, but its common variants rs9939609 may be associated with central nervous system diseases such as brain volume loss and alcohol dependence." (PMID 36118041, 2022). "Follow-up regression analysis of FTO SNPs homozygous individuals compared to heterozygotes variants carriers indicated that the additional allele did not contribute to a higher OR had a very weak contribution, indicating that the SNP association to obesity follows a dominant model." (PMID 36235854, 2022).